STAT3 (signal transducer and activator of transcription 3)
Diseases named in the same sentence as STAT3 in open-access papers (continued):
Sharing a sentence is not in itself a finding about the gene and the disease.
cancer (continued). "It has been reported that STAT3 acts as an important transcription factor in cancers." (PMID 28938560, 2017). "In combination, these studies suggest that the development of inhibitors against the Y239/240-ShcA phosphorylation sites may represent a therapeutic strategy to inhibit STAT3 activation in cancer cells and increase sensitivity to immunotherapies." (PMID 28276425, 2017). "STAT3 inhibition using LY5 has also been explored for treatment of drug-resistant cancer cells." (PMID 28750090, 2017). "We also found that pantoprazole inhibits the activation of the JAK2/STAT3 pathway and that a higher concentration of pantoprazole treatment displayed better efficacy in treating the muscle wasting induced by cancer cachexia by regulating the JAK2/STAT3 pathway." (PMID 28489606, 2017). "In addition, activation of STAT3 and inhibition of Bax activity via clusterin has been documented in hypothalamus, plasma, and cancer cells." (PMID 28767729, 2017). "Importantly, the inhibition of constitutively activated STAT3 induces cell apoptosis, identifying it as an effective target to combat cancer drug resistance." (PMID 28388577, 2017). "In addition, STAT3 promotes cancer development by promoting the self-renewal and differentiation of cancer stem cells (CSCs), which play crucial roles in tumorigenesis." (PMID 28738823, 2017). "Interestingly, a recent study indicated that the activation of the JAK2/STAT3 signaling pathway plays an important role in cancer cachexia, and the use of AG490, a JAK2 specific inhibitor, can improve the prognosis of cancer cachexia." (PMID 28489606, 2017). "Indeed, the JAK inhibitor ruxolitinib is currently in clinical trials for solid cancers and is closer to clinical approval for cancer therapy compared with other STAT3‐targeting agents." (PMID 28084011, 2017). "VEGF expression correlates positively with STAT3 activity in diverse human cancer cell lines." (PMID 28764703, 2017). "The present study aims to investigate the roles that TGF-β and IL-6/JAK2/STAT3 signaling play in cancer cell-MF interaction and how this interaction could influence cancer cell proliferation and disease progression in both in vitro and in vivo systems." (PMID 28819126, 2017). "Furthermore, miR-196b-5p promoted cancer stem cell properties and chemoresistance via activating STAT3 signaling pathway in vivo and in vitro." (PMID 28591704, 2017). "Taken together, these data suggested that STAT3 signalling is also blocked in the cancer group." (PMID 28350008, 2017). "JAK2/STAT3 signaling becomes deregulated in most cancers and is over activated in BTICs and GBM." (PMID 29253028, 2017). "Therefore, our data strengthen the rationale for targeting the SHP-1/STAT3 pathway as a novel anti-cancer therapy." (PMID 29029413, 2017). "STAT3 is known to play a role in cancer progression and stemness." (PMID 28689994, 2017). "Moreover, inhibition of STAT3 signaling reversed the increased expression of cancer stem cell factors by miR-500a-3p overexpression." (PMID 28750679, 2017). "To investigate the mechanisms by which SC‐60 inhibited cell growth and induced cell apoptosis in TNBC, we analyzed the protein expressions of p‐STAT3 and its downstream proteins that have been demonstrated to be involved in cancer cell proliferation and survival." (PMID 28084011, 2017). "Recent advances in STAT3 biology, however, suggest new aspects of STAT3 function in cancers." (PMID 29137356, 2017). "The apoptosis in STAT3 overexpressing cancer cells was reversed as well." (PMID 29029413, 2017).
cancer (continued). "Down-regulation of Hsp27 using OGX-427 (an antisense therapy) decreases cancer cell invasion, migration, phosphorylation of LL-6-dependent STAT3 (a major mediator of EMP in many cancer types) and nuclear translocation, as well as matrix metalloproteinase, thereby reversing EMT activity." (PMID 29295496, 2017). "Constitutive STAT3 activation is a major contributor to the pathogenesis of cancer." (PMID 28636670, 2017). "At present, an enormous amount of data strongly highlighted that inhibition of both NF-κB and STAT3 signaling, which are usually persistently activated in malignant tumors, could be potentially effective in suppressing inflammatory progression in cancers." (PMID 28331523, 2017). "Thus,the newly generated STAT3-blocked whole-cell HCC vaccine displayed the potential for cancer cell vaccinations." (PMID 29115974, 2017). "Further examination confirmed that both NF-κB and STAT3 signalling pathways were simultaneously repressed by cancer sera, suggesting that the attenuated NF-κB and STAT3 signalling could be the leading cause of DC dysfunction in cancer." (PMID 28350008, 2017). "Alterations in the amount of STAT3 interactors in the analyzed samples suggest a different behaviour of STAT3 which activity could correlate with the cancer progression in the tissue." (PMID 28489571, 2017). "STAT3 is abnormally expressed in pathological situations such as cancer." (PMID 28864784, 2017). "Therefore, further investigation of possible changes in c‐kit, c‐myc and STAT3 expression and function in other types of immune cells in human cancer are important." (PMID 28695716, 2017). "Therefore, we investigated if Stat3-mediated Nanog regulation was involved in the enhancement of cancer stemness by truncated HBx." (PMID 28186991, 2017). "Moreover, cytokine-driven JAK/STAT3 pathways are involved in cellular proliferation, differentiation, invasion, survival, and even inflammation and immune function of various human cancers." (PMID 28061445, 2017). "For example, chrysin, a major compound from Apis mellifera in Thailand, could sensitize A549 and HeLa human cancer cell lines to the apoptosis-inducing factor TRAIL by inhibiting STAT3 and downregulating Mcl-1." (PMID 28472978, 2017). "Hit compounds were confirmed in dose response experiments and further analyzed for their ability to inhibit STAT3 phosphorylation, downregulate STAT3- and STAT1-driven gene expression, and for their potential to impair the viability in STAT3-dependent and -independent cancer cell lines." (PMID 28636670, 2017). "Thus, SH003 regulation of STAT3 activation and complex formation would be crucial for the induction of autophagy and cancer treatment." (PMID 29179443, 2017). "As expected, overexpressing STAT3 in cancer cells was able to elevate the expression of CD163." (PMID 29152078, 2017). "STAT3 has been known to regulate autophagy, which is crucial for cancer development." (PMID 29179443, 2017). "Chronic STAT3 activation has been correlated with tolerance and cancer progression." (PMID 28827632, 2017). "Finally, for all the reasons mentioned before, another promising therapeutic strategy for MM, and for other cancers as well, consists in STAT3 targeting." (PMID 28435516, 2017). "These STAT3-mediated gene expressions in cancer cells promote angiogenesis." (PMID 28978186, 2017). "STAT3 pathway, essential for MM survival, contributed to cancer cell apoptosis by DHA." (PMID 28435516, 2017). "In addition to MAPK and AKT, signal transducer and activator of transcription 3 (STAT3) is another key regulator of cell survival and proliferation, as well as stem cell self-renewal in variant types of cancers." (PMID 28388589, 2017). "As a cancer prognostic marker, transcription factor STAT3 also presented binding sites." (PMID 28402947, 2017).
cancer (continued). "Clarifying the role of STAT3 and other kinases in CuB's anticancer activity may not only further its development as novel anticancer agent but also elucidate the role of STAT3 in cancer therapy." (PMID 27418139, 2017). "Several studies have found that some anti-cancer agents could inhibit STAT3 activation by generating reactive oxygen species (ROS)." (PMID 28054986, 2017). "PIAS3 is up-regulated by resveratrol treatment and inhibits STAT3 activation in cancer cells." (PMID 28978186, 2017). "Moreover, CMP treatment in mice significantly reduced the expression levels of ki-67, p-EGFR, and p-STAT3 in cancer tissues." (PMID 29212184, 2017). "Plumbagin, a vitamin K3 analogue, has also been reported to inhibit STAT3 signaling by induction of SHP-1 and may have potential to sensitize STAT3-overexpressing cancers to thalidomide and bortezomib." (PMID 28594363, 2017). "STAT3 has been shown to be involved in wound healing and cell migration of cancer cells, which might lead to invasion and metastasis." (PMID 28430601, 2017). "We hypothesized that the effect of C10 on viability/growth and migration of these cancers was related to its suppressive effect on TLR3 signaling which led to the inhibition of TLR-mediated STAT3 and Wnt5a signaling." (PMID 29371911, 2017). "STAT3 plays an important role in anti-apoptotic signaling within various cancer cells." (PMID 28877265, 2017). "Notably, NF-κB and STAT3 can cooperate to promote cancer development and progression, and also regulate distinct functions in surrounding non-tumorigenic cells." (PMID 28594363, 2017). "Moreover, STAT3 inhibition is a viable treatment option for drug-resistant cancers through inhibiting STAT3-mediated MDR1 gene expression." (PMID 28397855, 2017). "STAT3 is required and essential for tumorigenesis as shown in a variety of cancers." (PMID 28878571, 2017). "Previous studies have identified STAT3 as a valid target for cancer therapy." (PMID 28654902, 2017). "Recently, tri‐partite motif‐containing protein 8 (TRIM8) has been shown to interact with PIAS3, either by causing its degradation through the ubiquitin‐proteasome pathway or through its exclusion from the nucleus, resulting in enhanced STAT3‐dependent signaling in a subset of cancer cell lines." (PMID 28100038, 2017). "The newly generated STAT3-blocked whole-cell HCC vaccine has potential for cancer cell vaccination." (PMID 29115974, 2017). "Previous studies have demonstrated that STAT3 interacts with NF-κB in cancer cells." (PMID 29245972, 2017). "STAT3 is crucial in initiating and maintaining a procarcinogenic inflammatory microenvironment, both at the beginning of malignant transformation and during further cancer progression." (PMID 29029413, 2017). "Knowing that STAT3 plays an important role in cancer invasion, and that Cav-1 controls directional cell migration through STAT3, we next asked whether STAT3 activation was required for EF-directed migration of H1650-M3 cells." (PMID 29221162, 2017). "Signal transducer and activator of transcription factor 3 (STAT3) is cytoplasmic, that upregulates the expression of genes related to cancer proliferation, survival, and invasion, and is involved in the tumorigenesis, development, migration, and invasion of many solid tumors." (PMID 29226125, 2017). "These EMT-derived cancer cells exhibit elevated activation of STAT3 and enhanced aerobic glycolysis, with upregulation of certain enzymes and transporters related to glycolysis (such as MCT2); these cells also show downregulation of gluconeogenesis and some anabolic side-pathways." (PMID 28137309, 2017). "Both positive and negative associations between STAT3 activation and survival of lug cancer patients or lung tumor progression have been reported." (PMID 29126425, 2017).
cancer (continued). "Further upstream analysis revealed that cell signalling was disrupted in DCs from the cancer group, including attenuated canonical NF-κB and STAT3 signalling, which might result in abnormal target gene transcription." (PMID 28350008, 2017). "Some constituents of AR have been reported to exert anti-cancer properties by targeting STAT3." (PMID 28503147, 2017). "Our findings suggests that the IL-6/STAT3 signaling pathway activated by CAFs could be a promising target for anti-cancer therapies." (PMID 29100297, 2017). "The role of STAT3 in cancer development and drug response has been recently reviewed." (PMID 26910918, 2017). "Therefore, a strong interest has developed in STAT3 as a potent therapeutic target for cancer treatment." (PMID 28338101, 2017). "Importantly, increased levels of phospho-STAT3 were detected in patients with active UC, as well as in dysplasia and cancer, while a progressive decreasing trend of SOCS3 levels was observed from low-grade dysplasia to UC-CRC35." (PMID 28785079, 2017). "Thus, STAT3 has been an actively sought-after target for anti-cancer drug discovery, and a number of specific inhibitors have been developed for further clinical studies." (PMID 29179470, 2017). "In this regard, we investigated whether possible crosstalk between ROS and the STAT3 signaling pathway participated in the anti-cancer effect of SFN on GBM cells." (PMID 28054986, 2017). "Moreover, STAT3 is frequently activated in nearly 70% of different cancer types, including breast, lung, colon, prostate, cervical, renal, pancreatic, and ovarian cancers." (PMID 28245605, 2017). "STAT3 is also well-known for its role in cancer-related inflammation, immunity, and autophagy." (PMID 28085115, 2017). "We found that the effects of pantoprazole on cancer cachexia-induced muscle wasting may be associated with the inhibition of inflammatory cytokines and/or the inactivation of the JAK2/STAT3 and ubiquitin proteasome pathways." (PMID 28489606, 2017). "In the following work, we examined whether PMM-172 could affect the activity of STAT3 and viability in non-cancer cells." (PMID 28588262, 2017). "Given that inhibition of STAT3 homodimers formation diminishes STAT3 activity, STAT3 may represent a potential therapeutic target for LncRNA00364 in cancer chemotherapy." (PMID 29254221, 2017). "STAT3 signaling is a major pathway that connects inflammation to cancer." (PMID 27823965, 2017). "STAT3 plays a vital role in inducing EMT during progression of various types of cancer." (PMID 28617312, 2017). "Because GPRC5A expression is linked to inhibition of STAT3 and induction of differentiation, restoration of GPRC5A expression may provide a novel strategy for cancer prevention of HNSCC." (PMID 28270740, 2017). "Furthermore, we found that niclosamide not only inhibits STAT3 and Wnt/β-catenin signaling, which has been seen in other cancer cells, but it also down-regulates two other pro-survival signal pathways (PI3K/AKT and MAPK/ERK) in these cells." (PMID 28877265, 2017). "In addition, constitutive activation of STAT3 in cancer cells induces cell transformation via the inhibition of apoptosis and cell cycle activation." (PMID 29038437, 2017). "STAT3 is constitutively activated in various cancers, including HCC." (PMID 28413603, 2017). "MMP2, MMP9 are also secreted by cancer cells in a STAT3-dependant manner." (PMID 28978186, 2017). "VEGF expression correlates with STAT3 activity in diverse human cancer cell lines." (PMID 28978186, 2017). "Inhibition of NF-κB and Stat3 activation has become an effective therapeutic anti-cancer strategy." (PMID 28418913, 2017). "Moreover, the inhibitory effects of anti-miR-500a-3p on cancer stem cell phenotypes and activity of STAT3 signaling were reversed by silencing SOCS2, SOCS4 and PTPN11 in miR-500a-3p-downexpressing cells, respectively." (PMID 28750679, 2017).
cancer (continued). "Similar to what we found in the present study, it has also been shown that STAT3 inhibition in mice and human trials induced only moderate side effects in various cells and tissues, indicating that STAT3 is likely a suitable target for cancer therapy." (PMID 29179470, 2017). "We next explored whether Stat3 inhibition affects the viability of cancer cells with supernumerary centrosomes." (PMID 28474672, 2017). "Moreover, SH003 regulation of STAT3 signaling was crucial for the inhibition of cancer growth and metastasis." (PMID 29179443, 2017). "CD163 in cancer cells is involved in the progression and can be upregulated by STAT3." (PMID 29152078, 2017). "Given the current understanding that activation of STAT3 may also be the “hub” of the interplay among adipose tissue, inflammation, and cancer, our observations suggest that IL-6 may exert its “oncogenic” property through multiple pathways." (PMID 28077171, 2017). "Taken together, we propose that STAT3 may be an ideal candidate to target cancer invasion, metastasis and EGFR-TKI resistance." (PMID 29221162, 2017). "While mTOR has been shown to regulate STAT3/p63/Notch signaling in cancer cells, the molecular details of STAT3 modulation of AMPKα and/or mTOR activity remain unknown." (PMID 28686615, 2017). "Therefore, our results establish a mechanistic link between the inhibition of JAK2/STAT3 signaling and the anti-cancer therapy of targeting miR-196b-5p in CRC cells." (PMID 28591704, 2017). "In-depth analysis of hit compounds in chemical and biological assays demonstrated that the lead compound KI16 may be a promising agent to further develop towards a STAT3-targeted cancer therapeutic." (PMID 28636670, 2017). "Stat3 is an essential factor in cancer initiation, growth and metastasis." (PMID 28474672, 2017). "Thus, interference with STAT3 signaling pathway in cancer cells such as by antisense oligonucleotides and dominant-negative STAT3 mutants, has been shown to result in growth inhibition and the induction of apoptosis." (PMID 28430601, 2017). "It has been shown that niclosamide effectively limits different types of cancer growth both in vitro and in vivo by triggering apoptosis and oxidative stress or by inhibiting several important signaling pathways including Wnt/β-catenin, mTOR, NFκB, and STAT3." (PMID 28877265, 2017). "Suppressing the aberrant activation of STAT3 may at least slow down inflammatory diseases and even cancers." (PMID 29029439, 2017). "Several studies showed that STAT3 activation can promote stem cell-like properties in cancer cells." (PMID 29228728, 2017). "Therefore, TTB-induced DNA damage, apoptosis and reduced STAT3 activity occurs via ROS generation in cancer cells." (PMID 28245605, 2017). "Notably, as the major inflammation mediator, IL-6 is a dominant activator of STAT3 to promote cancer progression." (PMID 28036277, 2017). "Recent patents have indicated that thiazole derivatives show potent antitumor activity against different cancer cell lines through the inhibition of kinases, pro-matrix metalloproteinase activation, signal transducer and activator of transcription 3 (STAT3), the Bcl-2 family, and HDACs." (PMID 29280989, 2017). "Cell cycle control is a conserved role of Stat3 in animal development and cancer." (PMID 28222105, 2017). "Constitutively activated STAT3 plays an important role in oncogenic signaling and high expression level predicted poor prognosis, suggesting that inhibition of STAT3 may be an effective target for cancer therapy." (PMID 28455960, 2017).